FSTL3 (follistatin like 3)
Diseases named in the same sentence as FSTL3 in open-access papers (continued):
Sharing a sentence is not in itself a finding about the gene and the disease.
tumor (37 papers, 2009 to 2025). "In the unpaired analysis, the KRT81, KRT6A, and KRT17 genes, which were positively associated with FSTL3 expression, exhibited notably elevated expression in tumor tissues in comparison to that in normal tissues." (PMID 38240936, 2024). "The HRI signature consists of 11 HRDEGs, and we focused on the 5 key genes (RGS16, SNAI1, CDR2L, FRMD5, and FSTL3), which exhibited elevated expression levels in tumor tissues and are prognostic risk factors for CC." (PMID 36925652, 2023). "Taken together, these findings suggest an increased risk of poor health outcomes associated with high expression of FSTL3 in patients with CRC who experience tumour recurrence." (PMID 36807490, 2023). "FSTL3 has been confirmed as an oncogene closely associated with the proliferation and metastasis of the tumor cell." (PMID 34901156, 2021). "Second, modulation of FSTL3 expression in a human-mouse tumor xenograft model, suggests that higher levels of FSTL3 are linked to increased tumor growth and spread." (PMID 34425560, 2021). "The FSTL3 overexpression was found to significantly upregulate the surface markers of the M2 tumor-associated macrophages (TAMs) (CD206 and CD163)." (PMID 34901156, 2021). "Transcriptomic analysis of KPCA.FSTKO and KPCA.FSTKO_hFSTL3-derived tumor revealed that endogenous mouse Fst and Fstl3 were predominantly expressed by cancer-associated mesothelial and fibroblast cells, which are major components of the stromal tumor microenvironment." (PMID 41029436, 2025). "High expression of FOSB+, NEAT1+, or XIST+ tumor cell-associated genes such as FSTL3, VTN, PAPPA, CCN1, RRAD, and GPRIN3 may predict poor survival in patients with LUSC, suggesting that these genes act as prognosis biomarkers." (PMID 37430270, 2023). "Analysis of FSTL3 expression and the clinicopathological characteristics of the patients revealed a significant association between high FSTL3 expression and tumour size (T status, p < 0.001), lymph node invasion (N status, p < 0.001), and tumour stage (p < 0.001)." (PMID 36807490, 2023). "Previous reports have demonstrated that FSTL3 is linked to remodeling of the tumor immune microenvironment and may serve as a predictor of sensitivity to immunotherapy and chemotherapy." (PMID 37291533, 2023). "The expression level of FSTL3 is also associated with tumor angiogenesis." (PMID 36325361, 2022). "FSTL3 can be implicated in these phenotypes via the nuclear receptor transcription factor retinoic acid receptor (RARα), which can interact with target genes to regulate normal physiological processes, tumor growth, metastasis, drug resistance, and other processes." (PMID 36325361, 2022). "Additional molecular mediators, including GNG2, a tumor suppressor limiting brain metastasis and FSTL3, which promotes tumor progression via HIF1α-dependent pathways, have emerged as actionable biomarkers for metastatic control." (PMID 41403952, 2025). "We next sought to determine if the therapeutic response to PPC, and the corresponding decrease in tumor burden would be reflected in FST or FSTL3 levels in serum at endpoint." (PMID 41029436, 2025). "FSTL3 (follistatin‐like 3), a secreted glycoprotein, was observed to boost tumor growth and immune evasion in multiple cancers." (PMID 41395115, 2025). "Following implantation intraperitoneally at 1.10^6 cells/mouse, we observed that FSTL3 overexpression led to a 50% higher tumor mass in mice compared to the KPCA.FSTKO cells at day 10 post-graft." (PMID 41029436, 2025). "In immunocompetent tumor models, FSTL3 knockout led to an increased proportion of CD8+ T cells and a reduction in regulatory T cells and exhausted T cells, improving the efficacy of anti-PD1 therapy." (PMID 41029436, 2025). "Through the robust machine learning approaches, we developed a four‐gene model (MGP, LOXL2, FSTL3, and PFN2) reflecting key biological processes associated with inflammatory CAF activity and tumor aggressiveness." (PMID 41395115, 2025).
tumor (continued). "To evaluate fibrosis, we performed Sirius red staining, which confirmed that the tumors overexpressing FSTL3 exhibited a significantly higher collagen deposition within the tumor microenvironment, suggesting increased fibrotic areas within these tumors." (PMID 41029436, 2025). "Herein, we found that overexpression of FSTL3 changed the tumor microenvironment, leading to increased fibrosis and immune exclusion, and caused resistance to combination immunotherapy (PPC treatment)." (PMID 41029436, 2025). "To investigate the consequences of FSTL3 on tumor growth, we compared KPCA.FSTKO and KPCA.FSTKO_hFSTL3 derived tumors." (PMID 41029436, 2025). "We observed a significant increase in FST and FSTL3 serum levels by ELISA at endpoint compared to pre-graft levels in the KPCA tumor bearing mice (N=4 mice per group)." (PMID 41029436, 2025). "Thanks to the use of a human hFSTL3 transgene in the KPCA.FSTKO_hFSTL3 model, we were able to discriminate endogenous murine sources of Fstl3 in the tumor microenvironment." (PMID 41029436, 2025). "Longitudinal monitoring of FST and FSTL3 in serum, regularly tracked during tumor growth, revealed a similar upward trend for both proteins over time." (PMID 41029436, 2025). "This underscores the pivotal role of FSTL3 in cellular proliferation and survival, thereby impacting tumor initiation and progression." (PMID 38240936, 2024). "FSTL3 was found to be related to tumor invasion and metastasis in CRC by activating EMT 53, 54, and T-cell exhaustion and macrophage and fibroblast polarization." (PMID 39247594, 2024). "The findings indicated that the FSTL3 expression level in tumor tissues was considerably lower than that in normal tissues (p < 0.001) in both paired and unpaired examinations." (PMID 38240936, 2024). "Herein, we revealed that FSTL3 were overexpressed in malignant cells in the CRC microenvironment, notably, the expression level of FSTL3 was related to tumor immune evasion and the clinical efficacy of anti-PD1 therapy." (PMID 38302412, 2024). "The ablation of FSTL3 in CRC has a promoting effect on the creation of an anti-tumor microenvironment, which is mainly characterized by the improved anti-tumor efficacy of CD8+ T cells and repressed infiltration of regulatory T cells (Tregs)." (PMID 38302412, 2024). "Meanwhile, tumor mutation burden (TMB) and neoantigen load were significantly elevated in the group with high FSTL3 expression." (PMID 38302412, 2024). "In both TCGA and our validation set datasets, FSTL3 expression was notably reduced in tumor tissues compared to that in normal tissues." (PMID 38240936, 2024). "Using online tools like GEPIA, the correlations between FSTL3 expression and prognosis, clinical stage, survival status, and tumor-infiltrating immune cells were examined." (PMID 38240936, 2024). "The mRNA expression levels of RGS16, SNAI1, CDR2L, FRMD5, and FSTL3 were higher in tumor samples than that in adjacent normal tissues in TCGA-COAD cohort, suggesting that these five key genes participate in the progression of CC." (PMID 36925652, 2023). "Based on a comparison of the same cases, the expression of FSTL3 was significantly elevated in tumour tissues (p = 0.0038)." (PMID 36807490, 2023). "FSTL3 expression and tumour T status were significant predictors, as were lymph node status, distal metastasis, tumour stage, vascular invasion (emboli), and perineural invasion in the univariate analyses (p < 0.05)." (PMID 36807490, 2023). "Studies have found that FSTL3 can promote the metastasis of tumor cells by forming an inhibitory immune microenvironment, and promote the polarization of macrophages and fibroblasts." (PMID 37308925, 2023). "The results demonstrated that RGS16, SNAI1, CDR2L, FRMD5, and FSTL3 consistently exhibited significantly higher relative mRNA expression levels in CC tumor samples than in paired adjacent normal tissues." (PMID 36925652, 2023).
tumor (continued). "According to univariate analyses of DSS, tumour T status, lymph node status, distal metastases, tumour stage, vascular invasion (emboli), perineural invasion, and FSTL3 expression were significant predictors of poor outcomes (p < 0.05)." (PMID 36807490, 2023). "FSTL3 reportedly contributes to the development and progression of many cancers by promoting tumor metastasis, facilitating angiogenesis, and inducing stem cell differentiation." (PMID 36325361, 2022). "Studies have reported EMT changes in tumor cells exposed to short hairpin RNAs targeting FSTL3 (shFSTL3) in the human colon cancer cell line HCT116." (PMID 36325361, 2022). "As a member of the FST family, FSTL3 has been proved to play a critical role in human physiological process, non-tumor pathophysiologies and cancer." (PMID 36325361, 2022). "Here, we review the structure and function of FSTL3 in physiology processes, non-tumor pathophysiologies and cancers as well as potential clinical applications targeting FSTL3." (PMID 36325361, 2022). "The function and regulatory mechanism of FSTL3 in physiologies, various non-tumor pathophysiologies and cancer is complex." (PMID 36325361, 2022). "FSTL3 is often associated with the progression of malignant tumors by inducing the epithelial-mesenchymal transition (EMT), affecting the tumor microenvironment, influencing non-coding RNA regulation, and promoting angiogenesis." (PMID 36325361, 2022). "Because our findings highlighted that FSTL3 correlated with tumor malignancy, we next went on to investigate its prognostic value in CRC." (PMID 34335633, 2021). "The use of Luciferase labelling of tumour cells in combination with in vivo imaging allows a clearer study of the effect of FSTL3 on metastasis in vivo." (PMID 34901156, 2021). "Tumors were excised and examined visually: again, FSTL3 knockdown suggested smaller tumor size compared to parental MGC-803-derived tumors." (PMID 34425560, 2021). "It was discovered that FSTL3 enhanced tumor growth in mice, which manifested that the tumor volume and mass were larger than the NC group (P < 0.05)." (PMID 34555811, 2021). "The results showed that compared with adjacent normal tissue, FSTL3 protein was significantly overexpressed in tumor tissues (P = 1.6e-5)." (PMID 34335633, 2021). "The mRNA expression level of FSTL3 was markedly higher in the tumor samples than that in paired adjacent normal samples (P = 1.2e-07)." (PMID 34335633, 2021). "More importantly, FSTL3 was identified as a key factor in the remodeling of the CRC tumor microenvironment and a promising therapeutic target for blocking CRC metastasis." (PMID 34901156, 2021). "Down-regulated FSTL3 hampered the proliferation, invasion, EMT, and tumor growth of RCC cells and caused cell apoptosis." (PMID 34555811, 2021). "FSTL3 silencing decreased the capacity of forming the tumor cell clone as well as the sphere-forming abilities." (PMID 34901156, 2021). "We also assessed FSTL3 to the formation of cell colonies in culture, an important feature of tumor growth." (PMID 34425560, 2021). "The results of bioinformatics indicated a significantly positive correlation between FSTL3 and LBX2-AS1, and FSTL3 was evidently highly expressed in tumor tissue." (PMID 34858481, 2021). "Although some studies focused on the effects of RARα and FSTL3 on tumor development, much less has been understood on RARα/FSTL3 axis regulation on tumor." (PMID 34858481, 2021). "mRNA vaccines encoding these tumor antigens (THBS2, FSTL3, TNNT1, BGN, CTHRC1, and NOX4) induce a cell-mediated immune response and humoral immune response that are beneficial for efficient clearance of cancer cells." (PMID 35127707, 2021). "The tumor formation model in nude mice was erected through the subcutaneous injection of A498 cells transiently transfected with FSTL3-overexpressed plasmids, with the tumor growth in mice observed and recorded." (PMID 34555811, 2021).
tumor (continued). "Since FSTL3 is a potentially useful target gene for tumor therapy, it not only directly affects the biological characteristics of the tumor cells but also remodels the tumor microenvironment (TME) and influences the prognosis of the patient." (PMID 34901156, 2021). "We found that FSTL3 expression correlated to tumor nuclear grade, tumor size, and the number of reactive lymph nodes." (PMID 28178680, 2017). "FSTL3 expression was classified semiquantitatively and tested for possible correlation with age, menopause status, stage, tumor histological type and grade, estrogen receptor, progesterone receptor, and HER2 expression." (PMID 28178680, 2017). "Tumor samples were processed by immunohistochemistry to detect FSTL3 expression in tumor epithelium." (PMID 28178680, 2017). "Although FSTL3 expression correlated inversely to nuclear grade and tumor size, it was unrelated to other known prognostic factors such as disease stage and the number of metastatic lymph nodes, the latter being excluded by the multivariate analysis." (PMID 28178680, 2017). "The intensity of FSTL3 immunostaining also correlated inversely with tumor size (r = -0.366, p<0.001) and with the number of metastatic lymph nodes (r = -0.237, p = 0.004)." (PMID 28178680, 2017). "FSTL3 overexpression completely abrogated tumor response to PPC treatment (Prexasertib combined with PD-1 and CTLA-4 blockade) compared to controls, suggesting that FSTL3 may be involved in immunotherapy resistance." (PMID 41029436, 2025). "Importantly, through integrative machine learning approaches, we identified four hub genes (MGP, LOXL2, FSTL3, and PFN2) that are closely associated with tumor development and progression." (PMID 41395115, 2025). "• Serum levels of FSTL3 reflect tumor burden and therapy response in mice." (PMID 41029436, 2025). "While cancer cells express FST/FSTL3, our scRNAseq and spatial transcriptomic analyses suggest that tumor stromal cells may be the predominant source of this factor in the TME." (PMID 41029436, 2025). "This decline in murine FSTL3 may be due to a modest effect of PPC treatment on tumor burden reduction (fold change: 1.31), as observed at endpoint (p < 0.05), which failed to change survival." (PMID 41029436, 2025). "Next, we looked at whether high and low FSTL3 expression had the same effects on the tumor immune microenvironment." (PMID 38240936, 2024). "It suggests the potential of FSTL3 in cancer cells to affect tumor growth through tumor immunity." (PMID 38302412, 2024). "Low expression of SNAI1, CDR2L, FRMD5, and FSTL3 could induce cell viability and promote tumor cell apoptosis." (PMID 36925652, 2023). "Transformation of pluripotent stem cells to cardiogenic endothelial cells could be increased by FSTL3, but its role is unclear in tumor stem cells." (PMID 38025763, 2023). "The significance of PKM, a key enzyme in the final rate-limiting step of glycolysis, in tumor cell metabolism has now been extensively studied, whereas the potential function of FSTL3, an oncogene that has recently piqued the interest of researchers, in HCC has not been elucidated." (PMID 38044354, 2023). "FSTL3 was expressed more frequently in the tumour group than in the normal group." (PMID 36807490, 2023). "In summary, FSTL3 plays an important role in human non-tumor pathophysiologies and cancers, and may be targets of the potential clinical therapy." (PMID 36325361, 2022). "Therefore, FSTL3 has the potential to be used as a tumor-related marker to improve clinical decision-making." (PMID 36325361, 2022). "Understanding the role of FSTL3 in human non-tumor pathophysiologies and cancer may provide new ideas for exploring therapeutic targets for human diseases." (PMID 36325361, 2022).
tumor (continued). "By interacting with a disintegrin and metalloproteinase 12 (ADAM12), transforming growth factor-β ligands (activin, myostatin and growth differentiation factor (GDF) 11), FSTL3 can either activate or inhibit these molecules in human non-tumor pathophysiologies and cancers." (PMID 36325361, 2022). "However, the intrinsic detailed mechanism of FSTL3 in human non-tumor pathophysiologies and cancer requires further study." (PMID 36325361, 2022). "There was 30% reduction in tumor volume upon FSTL3 knockdown." (PMID 34425560, 2021). "Moreover, FSTL3 was recently found abundantly expressed in non-small cell lung cancer and breast cancer, and participates in tumor progression including invasion and metastasis." (PMID 34395416, 2021). "In addition, the FSTL3 overexpression is known to promote M2 macrophage infiltration in the tumor microenvironment." (PMID 34901156, 2021). "However, the role of FSTL3 in tumor progression and cancer immunology of CRC has been rarely studied." (PMID 34335633, 2021). "The expression levels of FSTL3 thus influences both cell proliferation and tumor progression." (PMID 34425560, 2021). "Studies have proved that FSTL3 is involved in modulating tumor progression." (PMID 34858481, 2021). "Altogether, these results suggested that FSTL3 may promote tumor progression and LNM by regulating inflammatory response and EMT via TGF-β signaling." (PMID 34335633, 2021). "Further analysis revealed 50% reduction in tumor weight upon FSTL3 knockdown." (PMID 34425560, 2021). "As far as we know, this is the first study on the role of FSTL3 in tumor stem cells." (PMID 33195193, 2020). "The index of FSTL3 immunostaining was inversely correlated to tumor size." (PMID 28178680, 2017). "However, the intensity of FSTL3 immunostaining correlated inversely with tumor size (r = -0.366, p<0.001) and with nuclear grade (p<0.01)." (PMID 28178680, 2017). "We hypothesized that FSTL3 overexpression in cancer cells not only modifies the cancer cell phenotype, but also modulates immunotherapy response through its action on stromal cell types of the tumor microenvironment." (PMID 41029436, 2025). "We hypothesized that FSTL3 overexpression contributes to immunotherapy resistance by altering the tumor microenvironment: promoting a more mesenchymal tumor phenotype, increasing fibrosis by promoting myCAF development, suppressing immunocyte infiltration, and promoting T cell exhaustion." (PMID 41029436, 2025). "Similarly, in oophorectomized mice, FST and FSTL3 levels rose significantly during tumor growth." (PMID 41029436, 2025). "Furthermore, FSTL3 was compared according to the differences between pathological manifestations; it was strongly correlated with tumour stage (p = 0.0017), tumour size (p = 0.0001), degree of cancer invasion of lymph nodes (p < 0.0005), and metastasis (p = 0.0429)." (PMID 36807490, 2023). "Hence, targeted therapy against FSTL3 may restore the body’s own anti-tumor immunity and the chemotherapy sensitivity in CRC." (PMID 34335633, 2021). "Thus, it can be supposed that FSTL3 may contribute to format a tumor-promoting microenvironment by negatively regulating immunity." (PMID 34335633, 2021). "Quantification in cell lines confirmed the knockout of FST and low expression of FSTL3, while in tumors, FST and FSTL3 expression were significantly higher in KPCA.FSTKO tumors, indicating stromal-derived expression within the tumor microenvironment." (PMID 41029436, 2025). "To investigate the consequence of FSTL3 overexpression on the composition of the TME we conducted an scRNAseq experiment in the KPCA.FSTKO and KPCA.FSTKO_hFSTL3 tumor models (day 10 post-graft)." (PMID 41029436, 2025). "IHC representative images from HPA database indicated that FSTL3 and PFN2 were highly expressed in tumor samples." (PMID 41395115, 2025).